GZMK (granzyme K)
Diseases named in the same sentence as GZMK in open-access papers (continued):
Sharing a sentence is not in itself a finding about the gene and the disease.
thyroid cancer (4 papers, 2021 to 2025). "According to our research, OR4D10, TREM2, and GZMK could all be genes associated with thyroid cancer." (PMID 40332815, 2025). "This suggests that the development of thyroid cancer is linked to GZMK, TREM2, and OR4D10." (PMID 40332815, 2025). "TREM2 was linked to M staging and pathological staging, OR4D10 was linked to T, N, and pathological staging, and GZMK was linked to T, N, M, and pathological staging, according to our analysis of the expression of these three proteins in the development of thyroid cancer." (PMID 40332815, 2025). "In particular, THCA thyroid cancer in the TCGA cohort had lower GZMK, higher TREM2, and higher OR4D10 expression compared to the adjacent tissues." (PMID 40332815, 2025). "The findings imply that elevated expression of GZMK, TREM2, and OR4D10 is linked to the hyperactivation of several oncogenic pathways in thyroid cancer, including those that regulate cell division." (PMID 40332815, 2025). "In this study, we aimed to comprehensively investigate the expression patterns, prognostic significance, and functional roles of GZMK, TREM2, and OR4D10 in thyroid cancer." (PMID 40332815, 2025). "GZMK, TREM2, and OR4D10 were strongly expressed in several kinds of malignancies including thyroid cancer." (PMID 40332815, 2025). "Specifically, in THCA, we observed lower GZMK and higher TREM2 and OR4D10 expression in tumor tissues compared to adjacent normal tissues, suggesting their involvement in thyroid cancer pathogenesis." (PMID 40332815, 2025). "In conclusion, our study provides new insights into the expression patterns and potential roles of GZMK, TREM2, and OR4D10 in pan-cancer, with a particular focus on thyroid cancer." (PMID 40332815, 2025). "To further understand the functions and pathways influenced by GZMK, TREM2, OR4D10, and all other mRNAs in thyroid cancer, we performed correlation studies using TCGA data." (PMID 40332815, 2025). "The current study presents a comprehensive analysis of the expression patterns and potential roles of GZMK, TREM2, and OR4D10 in pan-cancer, with a particular focus on thyroid cancer (THCA)." (PMID 40332815, 2025). "Our findings suggest that GZMK, TREM2, and OR4D10 may play important roles in modulating the immune response in thyroid cancer, potentially through their effects on leukocyte cell–cell adhesion and mononuclear cell differentiation." (PMID 40332815, 2025). "This suggests that GZMK, TREM2, and OR4D10 may be involved in the pathogenesis of thyroid cancer." (PMID 40332815, 2025).
bladder cancer (3 papers, 2022 to 2025). "The bias between either GZMK+ or GZMB+ cytotoxic CD4+ T cells has been observed in bladder cancer and CD4+CXCL13+ TFH-like cells in endometrial cancer." (PMID 41030456, 2025).
Clear Cell Renal Cell Carcinoma (3 papers, 2025). "Regarding our results from analyzing GZMK in Clear Cell Renal Cell Carcinoma, previous studies have also found higher expression of GZMK, with indications of T cell exhaustion." (PMID 40002821, 2025). "Notably, GZMK-expressing CD8+ T cells are positively correlated with the response to immunotherapy in clear cell renal cell carcinoma, esophageal cancer, and peripheral blood of non-small cell lung cancer patients." (PMID 40530387, 2025).
influenza (3 papers, 2008 to 2021). An acute viral infection of the respiratory tract, occurring in isolated cases, in epidemics, or in pandemics; it is caused by serologically different strains of viruses (influenzaviruses) designated A, B, and C, has a 3-day incubation period, and usually lasts for 3 to 10 days. "In contrast, expression of Granzyme K was significantly increased upon influenza vaccination." (PMID 29951069, 2018).
lupus nephritis (3 papers, 2022 to 2025). Glomerulonephritis in the context of systemic lupus erythematosus. "In addition, renal CD8+ T cells expressing GzmB or another granzyme, GzmK, have been identified in lupus nephritis patients." (PMID 35563816, 2022).
lymphoma (3 papers, 2016 to 2025). A malignant (clonal) proliferation of B- lymphocytes or T- lymphocytes which involves the lymph nodes, bone marrow and/or extranodal sites. "We propose that NKG7 exerts the same function in cytotoxic CD4+ T cells including TFK cells, leading to GZMK-mediated complement activation or GZMB-mediated activation-induced cell death of target – possibly lymphoma – cells." (PMID 41030456, 2025). "Here, we show that lymphoma samples contain cytotoxic CD4+ T cells, which were predominantly NKG7/TIA-1+GZMK+ TFH-like in FL and TIA-1+GZMK+ and/or GZMB+ within the CXCR5+PD-1+ and CXCR5–PD-1+ subpopulations of DLBCL." (PMID 41030456, 2025). "Granzyme K (GZMK) is expressed in cytotoxic T cells, therefore possibly reflecting a host anti-lymphoma response." (PMID 27708232, 2016). "Collectively, these findings suggest a differentiation trajectory from TFH to GZMK+ TFK to GZMB+ TFK and finally GZMB+CXCR5–CD4+ T-cell phenotypes during lymphoma progression, reflecting the convergence of cytotoxic CD4+ and CD8+ T cells into exhausted T cells." (PMID 41030456, 2025).
lymphopenia (3 papers, 2019 to 2025). Reduction in the number of lymphocytes. "We identified a specific CHIKV signature composed of 107 down-regulated genes that includes CX3CR1, BTLA, BCL2, GZMK and three genes that encode Fc receptor-like glycoproteins that could be related to the lymphopenia induced by CHIKV infection." (PMID 31211814, 2019). "The expression of KLRG-1 and GZMK was not increased with lymphopenia." (PMID 40612959, 2025).
multiple sclerosis (3 papers, 2013 to 2025). A progressive autoimmune disorder affecting the central nervous system resulting in demyelination. "Additionally, high levels of GZMK released from NK cells have been shown to play a protective role in multiple sclerosis by killing activated T cells associated with CNS inflammation." (PMID 23874874, 2013). "Consistently, CCR5+ GZMK+ CD8 T cells have been observed entering the CNS parenchyma of multiple sclerosis patients via GZMK-mediated transendothelial diapedesis." (PMID 40918115, 2025).
non-small cell lung carcinoma (3 papers, 2024 to 2025). A group of at least three distinct histological types of lung cancer, including non-small cell squamous cell carcinoma, adenocarcinoma, and large cell carcinoma. "Our study is the first to suggest that the effector CD8+ T cells, predominantly enriched in T-cell-dominant ascites, harbored the upregulated GZMK, which was recently identified as a marker of the precursor-exhausted T cells in non-small-cell lung cancer." (PMID 38460015, 2024). "In contrast, precursor-exhausted CD8+ TILs (Tpex) with high GZMK expression and diminished ICs accumulated within the responsive (R) TME after chemo+nivo in non-small cell lung cancer (NSCLC), while the nonresponsive (NR) TME was filled with exhausted Trm cells instead." (PMID 38343549, 2024).
atopic dermatitis (2 papers, 2024 to 2025). "In human atopic dermatitis, elevated granzyme K (GzmK) cleaves SDC-1, disrupting the glycocalyx and increasing VEGF secretion by keratinocytes." (PMID 41226609, 2025).
bacterial sepsis (2 papers, 2021). "Here we aim to understand the role of GzmK in a mouse model of bacterial sepsis and compare it to the biological relevance of Granzyme A (GzmA)." (PMID 34815792, 2021). "In conclusion, the role of GzmK in an in vivo mouse model of bacterial sepsis has been analysed for the first time and the biological relevance of GzmK and GzmA has been compared in bacterial sepsis." (PMID 34815792, 2021). "This is the first time that the role of GzmK in bacterial sepsis is analysed in vivo." (PMID 34815792, 2021).
dengue (2 papers, 2021 to 2024). "In humans, a cytokine signature involving early induction of granzyme K in the acute phase of primary dengue disease was strongly linked to induction of Th1-associated IgG3 as infection resolved." (PMID 39088280, 2024).
diabetes (2 papers, 2022 to 2024). "To assess the functional aspects of cytotoxic T cells, we calculated the cytotoxicity score for CD4 Tcyt and CD8 Tem using cytotoxic genes (PRF1, GZMH, and GZMK) and observed higher cytotoxicity scores in T2D patients compared to non-diabetes." (PMID 39072276, 2024).
Erythema (2 papers, 2024 to 2025). Redness of the skin, caused by hyperemia of the capillaries in the lower layers of the skin. "In the dermatitis mice, GzmK-/- mice display reduced scaling, erosions and erythema, with an associated improvement in angiogenesis and decreased microvascular damage." (PMID 40607408, 2025). "Accordingly, GzmK KO mice exhibited a reduced cumulative severity score (defined as combined erythema and desquamation severity scores) for the duration of the study and a significant decrease in cumulative severity score at day 7 compared to WT mice." (PMID 38903528, 2024).
Granuloma (2 papers, 2024 to 2025). A compact, organized collection of mature mononuclear phagocytes, which may be but is not necessarily accompanied by accessory features such as necrosis. "Although GZMKhi TEM/PEX-like cells were enriched in granulomas with dampened type 1 immune cellularity and inflammatory response, scRNA-seq analyses of disparate pathologies and tissues suggest GZMK CD8+ T cells promote and potentiate inflammatory sequelae." (PMID 39214090, 2024). "Immune and parenchymal cells in granuloma-rich right lungs demonstrated robust upregulation of genes related to immune activation, chemokine/cytokine signaling, and antimicrobial defense (CXCL, CCR, IL2, IRF4, GZMK)." (PMID 41586350, 2025).
leukemia (2 papers, 2025). A malignant (clonal) hematologic disorder, involving hematopoietic stem cells and characterized by the presence of primitive or atypical myeloid or lymphoid cells in the bone marrow and the blood. "We observed that there were fewer granzyme K+ CD8+ T effector cells and CD14+ monocytes in leukemia cell neighborhoods in responders than in nonresponders at baseline." (PMID 39975227, 2025).
Lyme disease (2 papers, 2025 to 2026). Lyme disease (named after the towns in the USA where the disease was first identified) is a bacterial infection caused by Borrelia burgdorferi. "Moreover, skin lesions (erythema migrans, an early clinical manifestation of Lyme disease) of patients with Lyme disease, a tick-borne zoonosis caused by Borrelia burgdorferi (B. burgdorferi), have a clonally expanded population of GzmK+CD8+T cells secreting IFN-γ but exhibit less cytotoxic action." (PMID 41009359, 2025). "Thus, GzmK+CD8+T cells secreting IFN-γ also comprise one of the first immune cells to fight against the invading bacteria responsible for Lyme disease." (PMID 41009359, 2025).
multiple myeloma (2 papers, 2025). "In addition, GZMK+CD8+ exhausted T cells are linked to a poor prognosis in multiple myeloma and inflammaging." (PMID 39777847, 2025). "It is worth mentioning that a recent study has reported the presence of highly exhausted GZMK+CD8+ T cells in the bone marrow of relapsed/refractory multiple myeloma patients." (PMID 39777847, 2025).
myocardial ischemia (2 papers, 2022 to 2025). A disorder of cardiac function caused by insufficient blood flow to the muscle tissue of the heart. "MiR‐145 was associated with MDD and targeted GZMK to regulate myocardial ischemia/reperfusion injury." (PMID 41291399, 2025). "Additionally, previous studies have shown that post-treatment with sevoflurane may prevent myocardial ischemia/reperfusion damage through the upregulation of miR-145 and downregulation of GZMK expression." (PMID 36034287, 2022).
osteosarcoma (2 papers, 2022 to 2024). A usually aggressive malignant bone-forming mesenchymal neoplasm, predominantly affecting adolescents and young adults. "CD4_C6_XIST cells express GZMK were recognized as the effector cells in osteosarcoma TME." (PMID 36305631, 2022). "Furthermore, the two CD8 + cytotoxic clusters demonstrated upregulation of NKG7, GZMB, GZMH, GZMK, CCL3, CCL4, and CCL5, suggesting that chemotherapy amplified the cytotoxic function of CD8 + T cells, potentially enhancing their antitumor activity within the osteosarcoma tumor microenvironment." (PMID 39033089, 2024).
Pleural effusion (2 papers, 2023 to 2024). The presence of an excessive amount of fluid in the pleural cavity. "CD8+T cells expressing granzyme K are preferentially enriched in pleural effusion, which may be involved in the occurrence of diseases." (PMID 37901241, 2023). "The lineage tracking in one study indicated that the CD4 + T- and CD8+ T-cell populations with distinct effector functions expanding at pleural sites and granzyme K-expressing CD8 T cells were preferentially enriched and clonally expanded in pleural effusion." (PMID 39664375, 2024).
primary Sjögren’s syndrome (2 papers, 2023 to 2025). "GZMK+CXCR6+CD8+ T cells are tissue-resident memory T (Trm) precursors that promote IgA+ B-cell antibody secretion in the labial glands of patients with primary Sjögren’s syndrome." (PMID 40659887, 2025).
prostate adenocarcinoma (2 papers, 2023 to 2024). "In addition, GZMK+CD8T, a hallmark of the aging immune population, occurred in all patients with prostate adenocarcinoma and the normal control." (PMID 38483933, 2024). "Mice grafted with prostate adenocarcinoma cells treated with MCTP-39, an inhibitor of the HMT WHSC1, showed increased NK cell effector function, CD107a, Granzyme-K (GZMK) and IFN-γ expression." (PMID 37090711, 2023).
pulmonary fibrosis (2 papers, 2023 to 2025). Chronic progressive interstitial lung disorder characterized by the replacement of the lung tissue by connective tissue, leading to progressive dyspnea, respiratory failure, or right heart failure. "Further study is required to determine the physiologic impact of granzyme K–producing memory CD8+ T cells, if any, on the development or progression of pulmonary fibrosis." (PMID 39989456, 2025).
triple-negative breast carcinoma (2 papers, 2024). An invasive breast carcinoma which is negative for expression of estrogen receptor (ER), progesterone receptor (PR), and human epidermal growth factor receptor 2 (HER2). "Through this association, it may be possible to discover new breakthroughs in the study of GZMK as a target in immunotherapy for triple-negative breast cancer." (PMID 38833021, 2024).
Achalasia (1 paper, 2023). A disorder of esophageal motility characterized by the inability of the lower esophageal sphincter to relax during swallowing and by inadequate or lacking peristalsis in the lower half of the body of the esophagus. "Analysis of differentially expressed transcripts of lymphocytes in achalasia showed that TRM, GZMK+ CD8+ T cells (Tc2), and GNLY+ CD8+ T cells had more DEGs than other lymphocytes." (PMID 37542039, 2023). "However, several cytotoxic enzymes and inflammatory cytokines, including GZMA, GZMB, GZMK, GNLY, and TNF were downregulated in TRM in achalasia, consistent with a previous study of TRM in MS42." (PMID 37542039, 2023).
acute myeloid leukemia (1 paper, 2025). Acute myeloid leukemia (AML) is a group of neoplasms arising from precursor cells committed to the myeloid cell-line differentiation. "GZMK was shown to be abundant in nivolumab-bound expanded CD8+ T cells in responding patients with renal cell carcinoma, and CD8+ GZMK+ cells were found to be significantly more abundant in patients with acute myeloid leukemia responding to ICI-based therapy compared to non-responders." (PMID 40187353, 2025).
Anxiety (1 paper, 2012). Intense feelings of nervousness, tension, or panic often arise in response to interpersonal stresses. "These genes may still be interesting candidate genes, when looking at monoamine availability (PCLO), or more specific (endo-)phenotypes like cortisol levels (ANPEP) and co-morbid anxiety (PTK2B and GZMK)." (PMID 22649524, 2012).
Ascites (1 paper, 2024). Accumulation of fluid in the peritoneal cavity (between the layers of the peritoneum that lines the abdomen). "Further investigation on how the GZMK+CD8+ T cells in ascites contribute to ascites development still needs to be conducted." (PMID 38460015, 2024).
B-cell NHL (1 paper, 2025). "Hence, an abundance of GZMA+GZMK+ cytotoxic CD4+ and CD8+ T cells was associated with poor survival of B-cell NHL patients." (PMID 41030456, 2025).
brain tumor (1 paper, 2023). "Down-regulated DEGs in recGBM were involved in cell proliferation (EGFR) and possibly brain tumor cell growth (BCAN), deadenylation of mRNA, which is linked to neurodevelopmental disorders (CNOT2), multi-drug resistance (ABCG2), and immune-related processes (GZMK)." (PMID 37189838, 2023).
cardiotoxicity (1 paper, 2025). Toxicity that impairs or damages the heart. "CDR3 sequences associated with the CD8 CD69 + PD-1 + T cell subset (cluster 10), characterized by elevated GZMK expression, were also identified in the CD8 GZMK + subset of cardiotoxicity patients (cluster 3)." (PMID 41510228, 2025).
catalepsy (1 paper, 2012). A nervous system disorder characterized by diminished responsiveness and consciousness, and rigidity of the body. "GZMK is part of a network of genes that are co-expressed higher in mice that have a high predisposition to freezing behavior or catalepsy." (PMID 22649524, 2012).
chronic rhinosinusitis (1 paper, 2024). Chronic form of sinusitis. "IL‐10+ GZMK+ CD4+ T cells have primarily been described in tumours, as well as nasal polyps from chronic rhinosinusitis patients." (PMID 38707998, 2024).
colon cancer (1 paper, 2024). "Our results also showed that GZMK+ resting NK cells highly infiltrate the cancer region, and this predicts a worse prognosis in patients with colon cancer." (PMID 39387546, 2024). "We next utilized mIHC to check those NK cells in the clinical tissue samples of a colon cancer patient with liver metastasis, confirming a high infiltration of GZMK+ NK cells and a low infiltration of KIR2DL4+ NK cells in live metastasis cancer." (PMID 39387546, 2024). "KIR2DL4+ activated NK cells were lessened in proportion with the progression of the disease from normal colon to colon cancer and liver metastasis cancer, whereas GZMK+ resting NK cells increased, suggesting that these two NK subsets were associated with metastasis." (PMID 39387546, 2024). "Interestingly, patients with colon cancer with higher infiltration of GZMK+ resting NK cells and lower infiltration of KIR2DL4+ activated NK cells exhibited shorter survival in the TCGA COAD cohort." (PMID 39387546, 2024). "(*: p<0.05, **:p<0.01, ***:p<0.001) (C) The signature scores of GZMK+ resting NK cells (upper) and KIR2DL4+ activated NK cells (lower) in colon cancer and liver metastasis in the spatial transcriptomic sections." (PMID 39387546, 2024). "Further analysis of NK cell subtypes revealed a dramatic change in KIR2DL4+ activated NK cells and GZMK+ resting NK cells, whereas no other NK cell subpopulations differed in colon cancer progression." (PMID 39387546, 2024). "ST analysis also confirmed that there was more infiltration of the KIR2DL4+ activated NK cell subset in the non-tumor area and GZMK+ resting NK cells in the tumor region, both primary colon cancer and liver metastasis." (PMID 39387546, 2024).
depression (1 paper, 2012). "Both PTK2B and GZMK have been linked to brain physiology and depression through animal models." (PMID 22649524, 2012).
E. coli infection (1 paper, 2021). "Next, we analysed the role of GzmA and GzmK in the control of E. coli infection." (PMID 34815792, 2021). "We have found that similarly to GzmA, GzmK did not play an important role in the control of E. coli infection." (PMID 34815792, 2021). "In addition, it has been observed that neither GzmA nor GzmK are involved in the control of E. coli infection." (PMID 34815792, 2021).
glioblastoma (1 paper, 2025). The most malignant astrocytic tumor (WHO grade IV). "GzmK+CD8+T cells are also highly present in the TME of glioblastoma (GBM) patients." (PMID 41009359, 2025).